IL6 (interleukin 6)
Diseases named in the same sentence as IL6 in open-access papers (continued):
Sharing a sentence is not in itself a finding about the gene and the disease.
tumor (continued). "In contrast, other cytokines, such as interleukin-6 (IL-6), interleukin-8 (IL-8), transforming growth factor-beta (TGF-β), and interleukin-10 (IL-10) have immunosuppressive effects and contribute to tumor progression." (PMID 40867268, 2025). "CAFs are activated by inflammatory mediators within the TME, encompassing soluble factors generated by the tumor, such as transforming growth factor beta (TGF-β), interleukin-1 (IL-1), interleukin-6 (IL-6), and tumor necrosis factor-alpha (TNF-α)." (PMID 39935427, 2025). "Inflammatory cytokines and chemokines, including IL-6, IL-8, CXCL9, CXCL10, and G-CSF, modulate tumor growth, angiogenesis, immune cell recruitment, and metastatic spread." (PMID 41149076, 2025). "Both TGFB2 and IL6 appear to serve as robust predictors in PDAC because they more directly drive and reinforce a tumor microenvironment that promotes aggressive disease." (PMID 40650134, 2025). "IL6 activates STAT3 and MAPK, promoting chemotherapyresistance, tumor progression,and immune evasion.It contributes to immunesuppression andsupports metastasis." (PMID 40427188, 2025). "In neutrophils, the activation of the JAK/STAT pathway is primarily mediated by cytokines such as IL-6, IL-17, GM-CSF, and IFN-γ, all of which are upregulated in the TME during tumor progression." (PMID 40486614, 2025). "The expression levels of pro-inflammatory and tumor-related genes, including VEGF, MMP9, TGF-β, TNF-α, COX-2, PGE2, and IL-6, were significantly downregulated in a dose-dependent manner following treatment with ATD-PLGA NPs compared to the untreated group." (PMID 40808199, 2025). "First, we examined the effect of IAPi on the expression of known factors involved in LKB1-mut tumor-immune responsiveness, including STING, IL-1α, IL-6, G-CSF, and PD-L1, 9,28,29,32." (PMID 40057483, 2025). "Under ER stress, PRKCSH-expressing tumor cells (PRKCSH [+]) exhibit moderate activation of the IRE1α–XBP1–JNK pathway and secrete IL-6 and IL-8, promoting tumor survival and supporting M2 macrophage polarization." (PMID 41350724, 2025). "To determine the source of IL-6, we considered prior findings that NIH3T3 cells can be induced into CAFs even when co-cultured with human-derived tumor cells, despite species differences." (PMID 40718440, 2025). "Within TME, inflammatory cytokines, in particular IL-6 and IL-8 (CXCL8), contribute to different tumor-promoting mechanisms, such as cancer cell plasticity, angiogenesis, and immunosuppression." (PMID 41306965, 2025). "Interleukin-6 (IL-6) and chemo-attractant protein 1 (MCP-1) are secreted by CAF, inducing tumor proliferation." (PMID 40214893, 2025). "We further found that tumor cells reshaped the TME by activating the IRE1α-XBP1s pathway, which in turn promoted IL-6 expression via XBP1s binding to the IL-6 promoter in the −1201 ~ −300 region." (PMID 41254082, 2025). "HSV expressing PTEN (HSV-P10, oHSV-P10) has been shown to regulate the PI3K/AKT and IL6/JAK/STAT3 signaling pathways, reduce PD-L1 expression in tumor cells, and decrease tumor immune escape." (PMID 40872965, 2025). "Similar immunosuppressive strategies are observed with other tumor-secreted factors such as IL-10, VEGF, G-CSF and IL6, which likewise limit APC activation and T cell-mediated anti-tumor immunity." (PMID 41488634, 2025). "IL-6 and PI3K/Akt/mTOR signaling both promote an immunosuppressive tumor microenvironment that can blunt the efficacy of ICIs." (PMID 41374963, 2025). "By inducing monocyte infiltration via SASP factors such as IL-6 and CXCL5, PAI-1 sustains an immunosuppressive TME, thereby facilitating tumor progression across a range of malignancies, including skin cancers." (PMID 41008624, 2025). "It has been reported that IL-6 and IL-1β can stimulate tumor cells to express CD274 (PD-L1) proteins via activating the STAT3 signaling pathway, thereby facilitating tumor cell immune escape." (PMID 39911394, 2025).
tumor (continued). "STAT3 is aberrantly activated in GBM, and IL‐6‐mediated STAT3 activation promotes immune evasion and tumor growth." (PMID 41354084, 2025). "Our findings reveal tumor-intrinsic mechanisms suppressing NK cell activity in NSCLC, proposing XBP1s, IL-6, and UBE2S as actionable targets to enhance NK-based immunotherapies." (PMID 41254082, 2025). "GSVA further confirmed the upregulation of angiogenesis, Hedgehog signaling, Kras signaling, inflammation (including inflammatory response and IL6‐JAK‐STAT3 signaling), Wnt‐β catenin signaling, and protein secretion in tumor‐derived epithelial cells." (PMID 40433916, 2025). "And for cell culture cytokine measurements, found that the SAA signaling significantly influenced the releasing of many T cell maturation/polarization and anti-tumor immunity related cytokines including, IL-1β, IFN-γ, TNF-α, IL-6 etc.." (PMID 41488634, 2025). "CAFs are central architects of the TME, driving tumor progression through extracellular matrix (ECM) remodeling, immunosuppression, and secretion of pro-tumorigenic factors (e.g., TGF-β, IL-6, CXCL12)." (PMID 40564985, 2025). "These CAFs contribute to chemoresistance and support CSCs by creating a niche rich in IL6 and IL8, which foster a pro-inflammatory environment that enhances CSC survival, drives drug resistance, and facilitates tumor progression." (PMID 40427188, 2025). "High IL-6 and CCL2 levels frequently correlate with worse clinical outcomes, reflecting a synergy among TANs, tumor cells, and other suppressive immune populations that ultimately restrict T-cell-mediated clearance." (PMID 40281554, 2025). "Glucose and fructose can induce the expression of pro-inflammatory cytokines such as interleukin-6 (IL-6) and tumor necrosis factor alpha (TNF-α), which play a role in the tumor microenvironment." (PMID 41374067, 2025). "Older adults exhibit persistent elevation of proinflammatory cytokines such as IL-6 and TNF-α, and impaired inflammation resolution mechanisms, which creates a pathological microenvironment that masks tumor-specific inflammatory signals." (PMID 40901675, 2025). "Consumption of germinated brown rice significantly reduced the IL-6 and TNF-α levels, thereby inhibiting inflammation and tumor development in the Gbrown group." (PMID 40869014, 2025). "This inflammatory state promotes the release of cytokines (e.g., IL-1β, IL-6, IL-10, IL-18, TNF-α) and growth factors that facilitate tumor cell proliferation, invasion, and angiogenesis, while simultaneously impairing immune surveillance." (PMID 41114747, 2025). "The IL6/JAK/STAT3 signaling axis is aberrantly activated in a wide range of tumors, and the transduction of this signaling axis promotes tumor cell invasion of surrounding tissues, resistance to drugs, and suppression of anti‐tumor immunity." (PMID 40874680, 2025). "CAAs are better equipped to support tumor invasion and metastasis by releasing CCL2, CCL5, CXCL8, IL-6, leptin, adiponectin, and VEGF." (PMID 40076892, 2025). "Meanwhile, SMARCB1 deletion led to the upregulation of the IL6/JAK/STAT3 signaling pathway, which activated the transcriptional activity of STAT3 and enhanced the proliferative and invasive abilities of tumor cells." (PMID 39995416, 2025). "CAFs can also exert indirect effects on cells within the tumor stroma through paracrine signaling as they secrete proteins such as chemokines (i.e. CXCL1), interleukins (e.g. IL-6) and growth factors (i.e. EGF) that influence immune response and proliferation." (PMID 40259388, 2025). "In OC, ascitic fluid contains high levels of IL6 and leukemia inhibitory factor (LIF), which trigger the formation of TAM-like cells from monocytes, further promoting tumor progression and metastasis." (PMID 40427188, 2025).
tumor (continued). "They promote tumor growth by remodeling the ECM to facilitate invasion, secreting pro-tumorigenic factors such as IL-6 and neuregulin 1 (NRG1) that enhance proliferation and therapy resistance, as well as fostering an immunosuppressive “cold” microenvironment." (PMID 41228234, 2025). "In vivo, co-injection of CD70-expressing fibroblasts with cSCC cells accelerates tumor growth, whereas CD70 knockdown impairs tumor progression and reduces PCNA, IL6, and MCP3 expression, confirming its functional relevance in the tumor microenvironment." (PMID 41510255, 2025). "For example, IL-6, a key NF-κB target, activates the STAT3 and MAPK pathways in tumor cells, promoting survival under hypoxic or nutrient-deprived conditions." (PMID 40562870, 2025). "By controlling IRE1α activity and IL-6/IL-8 secretion, these results imply that PRKCSH influences macrophage behavior and the inflammatory landscape of the tumor microenvironment in an indirect but significant way." (PMID 41350724, 2025). "Cytokine expression analysis revealed upregulation of IL-1α, IL-2, IL-4, and TNFα and downregulation of IL-6 and IL-8 in JX14P TAMs compared to JX14P-RT TAMs, suggesting that JX14P-RT TAMs have a higher capacity for tumor-promoting inflammation." (PMID 40386422, 2025). "IL-6 maintains JAK/STAT3 signaling, amplifying its own expression and promoting resistance to oxidative stress, tumor invasion, and chemoresistance." (PMID 41383608, 2025). "While acute DNA damage sensing initially stimulates anti-tumor immunity through Type I interferons, persistent signaling in senescent cells chronically drives a pro-tumorigenic SASP (e.g., IL-6, MMPs) that facilitates immune evasion and metastasis." (PMID 41516233, 2025). "Hypoxia-driven CCL26 and VEGF derived from Liver-CSC-derived recruit MDSCs to the TME in HCC, while tumor-secreted stem cell factor (SCF) and IL-6 expand MDSC populations and amplify immunosuppression." (PMID 41438763, 2025). "By inhibiting JAK1/2 and suppressing IL-6/STAT3 signaling, Momelotinib reduced tumor growth and metastasis." (PMID 41463071, 2025). "IL-6 is produced by multiple TME cell types, including tumor-infiltrating immune cells, stromal cells, and tumor cells." (PMID 40868199, 2025). "LPS activates Toll-like receptor 4 (TLR4), leading to NF-κB activation and the subsequent transcription of inflammatory mediators such as IL-6 and TNF-α, thereby fostering chronic low-grade inflammation and tumour progression." (PMID 40647494, 2025). "These EV-educated M2 macrophages secrete IL-6 and other factors that further reinforce STAT3 activation in a positive feedback loop while suppressing local anti-tumor immune responses." (PMID 40574836, 2025). "The expression of CD86 and CD206 as well as M2/M1 index were detected by FCM to identify TAM phenotype, while cytokines related to macrophage activation, including IL-6, TNF-α, and CXCL10, were determined in tumor tissue and serum after treatment." (PMID 39744236, 2025). "This analysis highlighted the consistent induction of pro-inflammatory cytokines such as IL-1β, IL-6, IL-8, IL-10, IL-17A/F, and TNF, which are known to play central roles in immune activation, macrophage polarization, and tumor–immune cell crosstalk." (PMID 41514627, 2025). "Mechanistically, senescent T cells exhibit upregulated glycolysis via SLC2A1/GLUT1 and SASP secretion (IL6/IL8), fostering tumor permissive microenvironments." (PMID 40781676, 2025). "For example, BCAAs can activate the NF-κB pathway, leading to the production of cytokines such as interleukin-6 (IL-6) and tumor necrosis factor-alpha (TNF-α), which can support tumor progression and alter immune responses." (PMID 40438606, 2025). "Like NK cells, macrophages produce pro-inflammatory cytokines like interleukin 6 (IL-6) and tumor necrosis factor-alpha (TNF-α), as well as reactive oxygen/nitrogen species, which are crucial for both innate host defense and tumor cell death." (PMID 40234973, 2025).
tumor (continued). "It is worth noting that AE can decrease pro-inflammatory cytokines in the tumor microenvironment, such as TNF-α, IL-6, and CRP, by modulating immune system responses, and these cytokines play a promoting role in tumor progression." (PMID 41480347, 2025). "Tumor cells and surrounding immune cells release cytokines such as tumor necrosis factor-alpha (TNF-α), interleukin-6 (IL-6), and interleukin-1β (IL-1β)." (PMID 41180630, 2025). "Activators such as IL‐6, IFN‐γ, and EGF stimulate the JAK/STAT pathway, which is critical for tumor progression and metastasis." (PMID 40166646, 2025). "Aging cells secrete inflammatory factors (such as IL-1α and IL-6) through SASP, which intensifies local inflammatory response and promotes the proliferation of tumor cells by activating NF-κB and STAT3 pathways." (PMID 40951350, 2025). "Pro-inflammatory cytokines, including interleukin-6 (IL-6) and tumor necrosis factor-alpha (TNF-α), further contribute to this microenvironment by creating a feedback loop that enhances tumor cell proliferation and survival." (PMID 40227814, 2025). "Through interleukin-6 (IL-6), TGF-β, and interleukin-21 (IL-21), the TME stomach myofibroblasts stimulate Th17 differentiation, which by secretion of IL-17 will promote tumor progression." (PMID 39940924, 2025). "These components not only facilitate intercellular tumour communication but also exert systemic effects through molecules such as TNF-α (Tumour Necrosis Factor), TGF-β (Transforming Growth Factor), IL-6, IL-10, and others." (PMID 41009413, 2025). "They secrete the Interleukins (IL-) IL-4, IL-6, IL-8, and IL-10, TGF-β (Transforming Growth Factor), EGF (Epidermal Growth Factor), and other factors that facilitate tumour growth and cell migration." (PMID 41009413, 2025). "In breast cancer cells, activation of TLR2 and TLR4 stimulates NF-κB, regulating the secretion of cytokines such as IL-6, TGF-β, VEGF, and MMP9, promoting tumor invasion, migration, and progression." (PMID 41200171, 2025). "Increased IL6 and TNFα expression in this study suggests that TGM7 silencing disrupts inflammatory regulation, creating a tumor-supportive microenvironment." (PMID 41425727, 2025). "We examined cytokine secretion profiles (IL-2, IL-4, IL-6, and IFNG) from activated T cells (CD69, IL-2RA, CD38, and HLA-DRB1) to evaluate T-cell activation in the CM tumor microenvironment, revealing consistently low expression levels." (PMID 40959090, 2025). "Survival was significantly longer in patients with higher baseline tumor infiltration of CD163 + macrophages and natural killer cells and in patients with reduced on-treatment circulating IL-6 levels or neutrophil-to-lymphocyte ratio." (PMID 40310569, 2025). "IL-6 upregulates CCR5 in MDSCs via the STAT3 pathway, whereas CCR5 is crucial in promoting tumor recruitment and activation of MDSCs." (PMID 40297580, 2025). "Preclinical work shows that NPs mediated modulation of bone marrow cytokines (e.g., IL-6, CXCL12) improves CAR-T infiltration and cytotoxicity, resulting in 40–60% superior tumor clearance compared with CAR-T alone in animal models." (PMID 41471085, 2025). "Mechanistically, long-term adrenergic stimulation through β2-AR can fuel tumor growth by increasing levels of VEGF, IL-6, and members of the MMP family, which changes how the extracellular matrix is remodeled and aids in metastasis." (PMID 41071399, 2025). "F. nucleatum can also induce the release of pro-inflammatory cytokines such as IL-6 and TNF-α, creating an inflammatory microenvironment that promotes tumor development." (PMID 40313460, 2025). "The development of HCC is strongly influenced by the tumor microenvironment (TME), characterized by elevated levels of pro-inflammatory cytokines (e.g., IL-6, TNF-α) and an enhanced immunosuppressive microenvironment contribute to HCC progression." (PMID 41422246, 2025).
tumor (continued). "In contrast, the expression levels of STAT3 downstream target genes—such as VEGFA, IL-6, MMP13, Bcl2, and Twist1—remained comparable across all experimental groups, likely due to tumor excision occurring at a stage when metastasis was already underway." (PMID 40806360, 2025). "Various cytokines, such as IL‐1, IL‐6, and TNF‐α, as well as adipokines such as leptin and adiponectin, significantly impact tumor cell proliferation and invasion." (PMID 39652453, 2025). "IL-6 is a key regulator of myeloid-derived suppressor cell (MDSC) aggregation and activation and promotes tumor cell proliferation, survival, invasion, and metastasis." (PMID 41051603, 2025). "Through activating the STAT3 signaling pathway, IL6 promotes critical processes such as angiogenesis, epithelial-to-mesenchymal transition (EMT), and immune evasion, all contributing to tumor progression and therapeutic resistance." (PMID 40427188, 2025). "In contrast, M2 TAMs are activated by type 2 T helper (Th2) cells, which secrete cytokines like IL-8, IL-6, and VEGF-A, fostering tumor growth." (PMID 40977686, 2025). "CAFs secrete immunosuppressive factors—including checkpoint proteins such as PD-L2 and FASL, as well as vascular endothelial growth factor (VEGF), TGF-β, IL-6, IL-11, and LIF—that dampen antitumor immunity and promote tumor progression." (PMID 41514658, 2025). "For example, TAM-derived IL-6, TNF-α and STAT3 signaling were believed to aggravate inflammation of TME and accelerate tumor advancement in PDAC and HCC." (PMID 40380196, 2025). "Dysbiosis-associated ligands (e.g., LPS, flagellin) activate TLRs to drive NF-κB and IL-6/STAT3 signaling, thereby amplifying tumor fitness, blunting antitumor immunity, altering antimicrobial-peptide programs, and increasing epithelial permeability." (PMID 41463208, 2025). "TAMs can produce different interleukins and factors, such as IL-6, IL-12, and TNF-α, through NF-κB-mediated signaling to induce the apoptosis of tumor cells." (PMID 41029711, 2025). "Many of them can act as factors enhancing tumor progression, activating angiogenesis (IL-1ß, TNF-α), tumor cell migration (IL-1ß, IL-6, IL-8), epithelial cell metaplasia (IL-6), and some stimulators and products of T regs (IL-10)." (PMID 40806737, 2025). "IL6 is frequently upregulated in GBM, where it activates JAK/STAT3 signaling to promote tumor cell survival, proliferation, and therapy resistance, and contributes to an immunosuppressive milieu." (PMID 41031155, 2025). "TGF-β promotes EMT and metastatic progression in lung cancer, while IL-6 activates signal transducer and activator of transcription 3 (STAT3) signaling to support tumor cell survival and proliferation." (PMID 41409273, 2025). "Approved IL‐6 inhibitors for RA are currently being investigated for use in cancers such as prostate cancer, where IL‐6–STAT3 signaling promotes tumor growth." (PMID 41208643, 2025). "Key inflammatory mediators within the tumor microenvironment include cytokines such as macrophage migration inhibitory factor (MIF), tumor necrosis factor-alpha (TNF-α), and interleukin-6 (IL-6)." (PMID 41011005, 2025). "Studies have demonstrated that EBV can induce the secretion of pro-inflammatory cytokines, such as IL-6 and TNF-α, which promote cell survival, angiogenesis, and tumor invasiveness." (PMID 40110195, 2025). "Beyond the various roles discussed in previous sections, IL-6 also promotes TAM polarization toward a pro-tumorigenic M2 phenotype and enhances secretion of cytokines and growth factors that support tumor invasion and metastasis." (PMID 40868199, 2025). "Omega-3s reduce the synthesis of pro-inflammatory cytokines such as TNF-α and IL-6, and suppressive factors like prostaglandin E2 (PGE2), which inhibit T-cell function in the tumor microenvironment." (PMID 40141831, 2025).